RNU6-301P (RNA, U6 small nuclear 301, pseudogene)
Gene: Small nuclear RNA gene on chromosome 14 (51,724,103 to 51,724,209, forward strand). Ensembl gene ENSG00000207004.
Homologues: Orthologues: chimpanzee U6 (99% identical), macaque U6 (94% identical), mouse Gm22443 (85% identical), pig U6 (80% identical), guinea pig U6 (77% identical). Paralogues in human: RNU6-35P (90% identical), RNU6-140P (89% identical), RNU6-16P (89% identical), RNU6-25P (89% identical), RNU6-1 (88% identical), RNU6-12P (88% identical), RNU6-13P (88% identical), RNU6-144P (88% identical), RNU6-17P (88% identical), RNU6-18P (88% identical), RNU6-2 (88% identical), RNU6-20P (88% identical), and 1283 more.